EGFR (epidermal growth factor receptor)
Diseases named in the same sentence as EGFR in open-access papers (continued):
Sharing a sentence is not in itself a finding about the gene and the disease.
melanoma (continued). "We simulated 3-day cell cultures, setting the maximal EGFR signaling as tenfold higher in CRC vs. melanoma cells (EGFRT = 1 vs. 0.1), based on EGFR mRNA expression from TCGA RNASeq data." (PMID 28649441, 2017). "The pERK “rebound” has been attributed, via gene knockout and inhibitor studies, to the activation of EGFR, which is expressed at much higher levels in CRC than in melanoma." (PMID 28649441, 2017). "We also found that epidermal growth factor receptor (EGFR), insulin-like growth factor-1 receptor (IGF-1R) and CRAF were over-expressed in VemR A375 melanoma cells." (PMID 27448964, 2016). "We showed that the activation of EGFR, and CAGE interactions with EGFR and HER2 were necessary for the resistance to taxol, gefitinib and trastuzumab in melanoma." (PMID 26863629, 2016). "Distinctive mechanisms related to the aggressive behavior of melanoma cells are the constitutive activation of growth factor receptors, such as c-Kit, PDGFR-α, EGFR, and the RAS/RAF/MEK/ERK pathway (or just MAPK pathway)." (PMID 27896217, 2016). "This conclusion is based on: 1) the down regulation of AXL, EGFR, IGF-1R and PDGFRβ in ShRUNX2 knocked down melanoma cell lines or RUNX2-specific U1 Adaptors-transfected melanoma cells." (PMID 27102439, 2016). "In the old situation within specialised hospitals, we assumed that multiple single-gene tests were performed, minimally three for NSCLC patients (a multigene panel, HER2/EGFR, and ALK, ROS, RET, or MET) and two for melanoma patients (BRAF and NRAS or KIT)." (PMID 27899957, 2016). "We showed that epidermal growth factor receptor (EGFR), insulin-like growth factor-1 receptor (IGF-1R) and CRAF were over-expressed in VemR A375 melanoma cells." (PMID 27448964, 2016). "1205LU melanoma cells exhibited reduced levels of RUNX2 expression at the two time points and a parallel decrease in EGFR and AXL expression." (PMID 27102439, 2016). "miR-217-CAGE loop serves as a target for the overcoming resistance to EGFR inhibitors and HER2 inhibitors in melanoma patients." (PMID 26863629, 2016). "Targeting FUT4/LeY mediated fucosylation by Rg3 inhibited the activation of EGFR/MAPK pathway and prevented melanoma growth." (PMID 25672851, 2015). "In melanoma, the autocrine and paracrine actions of EGF and EGFR contribute to tumor cell proliferation and migration." (PMID 26079945, 2015). "Upregulation of various RTKs or their ligands have been reported in MAPK-inhibitor resistant melanoma, including PDGFRβ, IGF-R1, HGF, FGFR2, NRG1 and the EGFR family (EGFR, ERBB2, ERBB3, ERBB4)." (PMID 26426052, 2015). "We found that Rg3, FUT4 siRNA and Rg3 combined with FUT4 siRNA led to reduced activation of EGFR and ERK1/2 in A375 melanoma cells." (PMID 25672851, 2015). "We investigated the effect of ganetespib on signaling molecules that have been reported to be the clients of HSP90, including c-Met, EGFR, and IGF-1R, in a panel of five melanoma cell lines." (PMID 23418523, 2013). "An activated EGFR/AKT pathway and the expression of survivin contributed to a lower sensitivity in response to BA treatment in human melanoma cells." (PMID 21906280, 2011). "From the perspective of comparative pathobiology, although mutationally altered EGFR is not the primary culprit in human melanoma, the Xmrk oncogene is upstream from and orchestrates many of the same signaling cascades known to be activated in human melanoma, such as the MAPK pathway." (PMID 20230482, 2010). "In the present study, we designed a strategy to overcome barriers in solid tumor therapy by employing a combinatorial regimen consisting of DTIC followed by infusion of engineered EGFR mCAR T cells after lymphodepleting pre-conditioning with CPA, using a B16 melanoma model." (PMID 41516067, 2025). "Taken together, these data suggest that all mutants were correctly expressed and normally responded to EGF stimulation, and C797S mutation did not enhance the autophosphorylation of T790M/L858R in EGFR-negative melanoma cells." (PMID 40649937, 2025).
melanoma (continued). "Fitness penalties have been demonstrated in BRAF-resistant melanoma and EGFR-resistant metastatic colorectal cancer but have not been defined during the evolution of resistance to common cytotoxic therapies like platinum chemotherapy." (PMID 40299825, 2025). "EGFR-induced RAS/AKT/MEKK3 and NF-κB signaling inhibit apoptosis in melanoma cells." (PMID 38534309, 2024). "This has led to extensive studies on the combination of various small-molecule drugs, including epidermal growth factor receptor inhibitors in esophageal squamous cell carcinoma, BRAF or MEK inhibitors in melanoma, ALK inhibitors in neuroblastoma, and immune checkpoint inhibitors." (PMID 39000513, 2024). "Targeting BCL‐xL‐/BCL‐2 could sensitize tumour‐resistant cells to EGFR inhibitors, or result in the inhibition of actin remodelling molecules counteracting adaptive resistance to BRAF inhibitors in melanoma." (PMID 38693863, 2024). "Histological examination of the brain tumor showed neural differentiation markers (thyroid transcription factor 1 (TTF-1), cytokeratin 7 (CK7), AE1/AE3, and epidermal growth factor receptor (EGFR)) with negative melanoma markers." (PMID 39192931, 2024). "EGFR and HER2 in both resistant melanoma cell lines were significantly elevated on mRNA level." (PMID 39175042, 2024). "The activation of the RAS signaling pathway by EGFR in cancer is well known; however, in CM, there is limited information available on the role of this tyrosine kinase receptor (TKR), apart from its expression in melanocytic nevi and some melanomas." (PMID 38396984, 2024). "We performed RNA-seq on EGFR-mutant PC9 NSCLC cells treated with the EGFR inhibitor gefitinib and BRAF-mutant SKMEL28 melanoma cells treated with the BRAF inhibitor dabrafenib to investigate the scope of the transcriptional changes in each system and to uncover shared mechanisms of drug tolerance." (PMID 38473364, 2024). "Tissue‐specific differences in EGFR expression contribute to different efficacy of treatment, with CRC originating from high EGFR‐expressing epithelial cells, while melanoma arises from EGFR nonexpressing neural crest cells." (PMID 39073010, 2024). "The underlying molecular mechanisms call into play the upregulation of epidermal growth factor receptor (EGFR) and EGFR2, thus defining for this alarmin a role as a putative growth factor for melanoma cells, promoting their proliferation, migration, and invasion." (PMID 38775220, 2024). "Likewise, introduction of HDAC8 into melanoma cell lines with low endogenous HDAC8 expression increased phospho-Jun and EGFR levels." (PMID 38030596, 2023). "Among melanoma cell lines, WM983A cells isolated from the primary vertical growth tumor of a melanoma patient do not express detectable endogenous EGFR at the protein level." (PMID 37333807, 2023). "Colorectal NECs have similar EGFR methylation signatures to melanoma, unlike CRC, and BRAF inhibitor monotherapy showed much higher tumor regression in colorectal NECs than CRC in patient-derived xenograft models." (PMID 37422534, 2023). "Similar findings were observed in human melanoma cells (A375), with reduced migration and invasion, where RA (555 μM) inhibited ADAM17 (disintegrin and metalloprotease 17), EGFR (epidermal growth factor receptor), p-Akt and p-GSK3β (glycogen synthase kinase-3 β) expressions." (PMID 36675206, 2023). "Several of the EMT-related genes with higher expression in NR patients encoded for molecules controlling adhesion (ITGB3, VCAM1, collagens, and others), interaction with extracellular matrix (VEGFA, MMP14, WNT5A, LAMA1, and others), and melanoma de-differentiation (KRT9, KRT10, EGFR, and others)." (PMID 37739939, 2023). "Melanoma patients with high expression of BIRC5, EGFR, and ATG9B had a worse prognosis." (PMID 36690663, 2023).
melanoma (continued). "To study the function of wild type (WT) and mutant EGFRs, we chose melanoma cell lines WM983A in which their endogenous EGFR protein levels are almost non-detectable compared to other melanoma lines IgR3 and WM852." (PMID 37333807, 2023). "Among all cell lines tested in this study, FGFR1 was highly expressed in EGFR + NSCLC NCI-H1650, HCC827, NCI-H1975, and HER2 + BC HCC1569 cells and BRAF+melanoma RPMI-7951, IGR-39, and SK-MEL-3 cells, and FGF2 was highly expressed in NCI-H1650, HCC827, HCC1569, RPMI-7951, and IGR-39 cells." (PMID 37880373, 2023). "In addition, RTK (EGFR), E-cadherin (CDH1), and MITF are also involved in the transformation of normal melanocytes to benign moles, atypical hyperplasia moles, and melanoma." (PMID 35893303, 2022). "Since EGFR mediates resistance to BRAF inhibitors, the differing expression of EGFR in CRC, compared to melanoma, may explain this difference in response rates." (PMID 36530921, 2022). "Canertinib (also known as CI-1033) is an irreversible inhibitor of the four members of the epidermal growth factor receptor (EGFR) tyrosine kinases, shown to inhibit tumour cell growth, and to induce cell apoptosis in several cancer models, such as melanoma and BC." (PMID 36009536, 2022). "However, similar to other TKR important in melanoma such as AXL and EGFR, ROR2 does alter the expression of numerous proteins in melanoma and other cancers." (PMID 36127680, 2022). "sgRNAs targeting EGFR or SLC35B2, respectively, were depleted only in YAP5SA cells treated with Vemurafenib, but were not substantially changed in untreated YAP5SA cells or parental melanoma cells (EV)." (PMID 35798875, 2022). "However, given the link of large oncosomes to cell metabolism and EGFR/AKT1 pathways, their role in melanoma merits further exploration." (PMID 35804857, 2022). "EGFR expression has been shown to mediate melanoma resistance toward BRAFV600E inhibitors and not to be beneficial in the absence of Vemurafenib." (PMID 35798875, 2022). "Interestingly, simultaneous inhibition of tyrosine phosphorylation of EGFR and SRC kinases can overcome the frequently developing BRAF resistance in melanoma." (PMID 35208960, 2022). "In addition, hyperphosphorylation of mTOR at its threonine Thr2446 and serine residues (Ser2448 and Ser2481) occurred both via the EGFR-ERK-S6K1 axis and the PI3K/AKT axis and is related to growth in various types of cancers and melanoma." (PMID 35208960, 2022). "The efficient combined targeting of EGFR, SRC, STAT, and MAPK by 3, 3′- (3, 5-DCPBC) in melanoma cells may long term assist clinicians to prevent melanoma growth and even to overcome drug resistance." (PMID 35208960, 2022). "Previously, ‘driver-negative’ (i.e. the absence of BRAF, NRAS, KIT, GNAQ or GNA11 mutations) melanoma cell-lines that were less sensitive to trametinib and which displayed paradoxical activation of MEK1/2, were found to show basal EGFR activation due to AREG." (PMID 35993275, 2022). "When EGFR was transiently silenced in B16F10 cells via the introduction of small interfering RNA (siRNA) or by adding the recombinant chimeric EGFR monoclonal antibody Cetuximab in the presence of ALOC-EO, melanoma growth was inhibited." (PMID 34360915, 2021). "GST mu3 is an enzyme expressed in the skin that detoxifies oxidative stress products generated from exposure to UV irradiation; however, its signaling characteristics in melanoma concerning EGFR have not yet been characterized." (PMID 34067095, 2021). "Particularly, a hyperactivation in EGFR and MET in cells with acquired resistance to BRAF inhibitors was shown; consequently, this combination (lapatinib+foretinib) was tested for its efficiency in BRAF resistant melanoma cells." (PMID 33918490, 2021).
melanoma (continued). "Besides, studies have shown that EGFR and its downstream pathways are involved in the tumorigenesis of many cancers (such as Ras-MEK-HSF1 axis regulates the development of melanoma)." (PMID 33422093, 2021). "Indeed, GLI2 was found to play a major role in suppressing MITF expression in human melanoma specimens, and the expression of GLI1/2 was correlated with EGFR/AXL signatures." (PMID 34572373, 2021). "Based on the results, we speculated that RA could target ADAM17 to down-regulate its expression therefore inactivate ADAM17/EGFR/AKT/GSK3β axis, ultimately exerting anti-cancer effects on melanoma in vitro." (PMID 34224305, 2021). "Melanoma cells instead express low levels of EGFR and are therefore not subject to this feedback activation." (PMID 34630336, 2021). "Likewise, in the context of targeted therapies, increased oxidative stress is observed in melanoma cells resistant to BRAF inhibition, while autophagy supports drug resistance against EGFR-targeted therapies in EGFR-driven cancer cells." (PMID 33807785, 2021). "When we treated melanoma cells with forskolin, a strong stimulator of the cAMP pathway that leads to MITF activation as visible by MLANA expression, the H2O2-mediated upregulation of EGFR was prevented." (PMID 33916908, 2021). "COMMD5 as a tumor suppressor regulates several tumorigenic kinases: it inhibits epidermal growth factor receptor (EGFR) expression and phosphorylation in kidney cancers and suppresses the MAPK and PI3K/AKT signaling pathways in renal carcinoma and melanoma cells." (PMID 34943955, 2021). "Furthermore, NRF2-ko cells showed reduced EGFR phosphorylation, indicating that NRF2 is important for full EGFR pathway activity in melanoma." (PMID 33916908, 2021). "The downstream of EGFR, the MAPK pathway, stimulates the activation of NF-KappaB heteromorphs and homodimers to drive the expression of iNOS, thus supporting the occurrence of melanoma." (PMID 33732282, 2021). "Furthermore, the activity of receptor tyrosine kinases including EGFR, another efficient MEK/ERK1/2 activator, is suppressed in melanoma under normal circumstances." (PMID 33916908, 2021). "The knowledge that the biology is more complex and heterogeneous in CRC than in melanoma is supported by several preclinical data suggesting that, differently from melanoma, CRC cell lines express high levels of activated EGFR, which convey a reactivation of MAPK pathway following BRAF inhibition." (PMID 34299337, 2021). "This feedback is observed only in colorectal since melanoma cells express low levels of EGFR and are therefore not subject to this reactivation." (PMID 33507915, 2021). "In addition to NRAS mutations, several receptor tyrosine kinases (RTKs) such as c-KIT, EGFR, MET, and VEGFR have been reported to be involved in melanoma progression, invasion, or resistance to therapies, mainly targeting the MAPK pathway." (PMID 33918490, 2021). "To investigate the possibility that melanoma cells modulate HB-EGF and/or EGFR expression to evade drug-induced cell death, we examined the expression of HB-EGF and EGFR after treatment with the anti-myelosuppressive drugs doxorubicin (DOX) and bortezomib (BTZ)." (PMID 34360915, 2021). "Like the proinvasive receptor tyrosine kinase AXL, EGFR is expressed in dedifferentiated melanoma cells in a negative correlation with the melanocytic lineage factor MITF." (PMID 33916908, 2021). "These are EGFR, ERRFI1, IL6, JAK2, PLXNC1, RGL3 which were found to be upregulated and CBL, CDC42, PIK3R3, STAT3, UBE2D2 and YWHAZ which were found to be downregulated; Melanoma has PLXNC1 as upregulated and TGFA as downregulated gene." (PMID 34764329, 2021). "Not surprisingly, as for Gal-1 silencing, EGFR impairment did not basally affect the viability of drug-sensitive parental melanoma cells." (PMID 32784465, 2020).
melanoma (continued). "Epidermal growth factor receptor (EGFRErbB-1; HER1), a transmembrane protein that is a receptor tyrosine kinase for members of the epidermal growth factor family (EGF family) ligands, is reportedly involved in the autocrine growth of melanoma cells." (PMID 32605090, 2020). "The lack of confirmed objective responses in BRAF mutant CRC, in contradistinction to melanoma, to the RAF dimer inhibitor lifirafenib which inhibits all RAF isoforms as well as EGFR and KRAS supports this hypothesis." (PMID 32922659, 2020). "Fibroblast growth factor receptor 3 (FGFR3) may promote melanoma growth, metastasis, and EMT behavior by influencing the phosphorylation levels of ERK, AKT, and EGFR." (PMID 33240619, 2020). "By decreasing the expression levels of EGFR, IGF-1R, CRAF, miR-7 could inhibit the activation of the MAPK and PI3K/AKT pathways and reverse melanoma cell resistance to BRAFi." (PMID 32054078, 2020). "In melanoma, KLF6 overexpression reduced the expression of EGFR protein." (PMID 32552913, 2020). "EGFR, HER3 and HER4 overexpression is correlated with poorer prognosis in human melanoma." (PMID 31996230, 2020). "Anaplastic lymphoma kinase (ALK) gene rearrangement testing was performed in patients with adenocarcinoma who were EGFR negative; BRAF was performed in patients with melanoma, and C-MYC mutations in patients with lymphoma." (PMID 31429741, 2019). "Concordant with this, the EGFR inhibitor AG1478 displayed no impact on cell proliferation, indicating that CXCR7 facilitates melanoma cell proliferation independent of EGFR." (PMID 30804329, 2019). "Although we did not observe the intrinsic phosphorylation of EGFR in any cell line, the differences in the response of the melanoma cells with SIRT2-downregulation to EGF was evident." (PMID 31091806, 2019). "We also found that higher EGFR expression indicates elevated migration but not proliferation of melanoma cells." (PMID 31514305, 2019). "Moreover, to our knowledge, first data on successful combination of carbon ion EBRT and EndoRT (CERT) utilizing 131I-labelled monoclonal anti-EGFR Cetuximab in A431 and small molecule approach with 131I-Benzamide in B16F10 melanoma model is reported." (PMID 30042828, 2018). "Based on our results, we conclude that both EGFR and MET receptors might be effective targets in melanoma therapy." (PMID 29719603, 2018). "Next, we decided to examine the proapoptotic effect of EGFR and MET inhibitors on melanoma cells." (PMID 29719603, 2018). "The aim of the study was to evaluate any possible correlation between mutations in main growth-controlling genes (BRAF, NRAS, CDKN2A) and copy number variations in frequently amplified candidate genes (MITF, EGFR, CCND1, cMET, and cKIT) during melanoma initiation and progression." (PMID 29492214, 2018). "BRAF-mutant COADREAD (7.6% of patients) presents a similar problem in that BRAF inhibitor monotherapy is ineffective unlike in BRAF-mutant melanoma and that triple drug combination targeting the EGFR, MAPK, and PI3K pathway has shown more positive results." (PMID 30053901, 2018). "We selected four EGFR-positive murine tumors from different histological origins (CT26, colon; 4T1 and F3II, mama; D122, lung) and included melanoma B16F10 cells as negative control for EGFR expression." (PMID 29056908, 2017). "This has been attributed to the expression of EGFR which occurs in some colorectal cancers, but not in melanomas." (PMID 28637487, 2017). "Additionally, the ERBB family members EGFR, ERBB1, ERBB2 and ERBB3 are known to be involved in driving several oncogenic processes in melanoma." (PMID 28223541, 2017). "On the contrary, melanomas do not express EGFR but forced expression of EGFR in melanoma cells leads to resistance to vemurafenib." (PMID 29312543, 2017). "Reduced levels of the receptor tyrosine kinases IGF-1R, FGFR1, PDGFRβ, and EGFR were detected in the RUNX2 knocked down 1205LU melanoma cells as compared with the non-silencing (control) ShRNA-expressing 1205LU cells." (PMID 27102439, 2016).